CEP70 (centrosomal protein 70)
Description:
Plays a role in the organization of both preexisting and nascent microtubules in interphase cells. During mitosis, required for the organization and orientation of the mitotic spindle.
Synonyms: BITE; FLJ13036
Tractability: PROTAC: ubiquitination databases record sites on it.
Gene: Protein-coding gene on chromosome 3 (138,494,339 to 138,594,538, reverse strand). Ensembl gene ENSG00000114107.
Subcellular location: Cytoplasm, cytoskeleton, microtubule organizing center, centrosome
Subcellular location (Human Protein Atlas): Cytosol; Nucleoplasm; Primary cilium; Basal body; Centrosome
Pathways (Reactome):
Cell Cycle: AURKA Activation by TPX2; Loss of Nlp from mitotic centrosomes; Loss of proteins required for interphase microtubule organization from the centrosome; Recruitment of NuMA to mitotic centrosomes; Recruitment of mitotic centrosome proteins and complexes; Regulation of PLK1 Activity at G2/M Transition
Organelle biogenesis and maintenance: Anchoring of the basal body to the plasma membrane
Gene Ontology:
Molecular function: identical protein binding; protein binding; gamma-tubulin binding
Biological process: cilium assembly; regulation of microtubule cytoskeleton organization
Cellular component: centrosome; cytosol; microtubule organizing center
Genetic constraint (gnomAD): Loss-of-function variants: 25 observed, 32.42 expected, observed/expected ratio (o/e) 0.77, 90% interval 0.56 to 1.08. The upper end of that interval is the gene's LOEUF score, 1.08, which puts it in group 4 of 6, group 1 being the genes least tolerant of losing a copy. Missense variants: 332 observed, 345.66 expected, observed/expected ratio (o/e) 0.96, 90% interval 0.88 to 1.05. Synonymous variants: 108 observed, 118.04 expected, observed/expected ratio (o/e) 0.91, 90% interval 0.78 to 1.07.
Homologues: Orthologues: chimpanzee CEP70 (98% identical), macaque CEP70 (96% identical), dog CEP70 (85% identical), guinea pig CEP70 (82% identical), mouse Cep70 (79% identical), rat Cep70 (76% identical), tropical clawed frog cep70 (38% identical), zebrafish cep70 (32% identical).
Diseases named in the same sentence as CEP70 in open-access papers:
CEP70 is named in the same sentence as 28 diseases in open-access papers, as found by Europe PMC text mining. Sharing a sentence is not in itself a finding about the gene and the disease. The quoted sentences say what the papers report.
breast carcinoma (3 papers, 2014 to 2024). "However, it remains elusive whether Cep70 is implicated in the sensitivity of the anti-microtubule drug paclitaxel in breast cancer." (PMID 28632150, 2017). "KCZ+BZA co-treatment reduced protein expression of Cep70, UPF3A, and RRas2, shedding new light on the underlying mechanism of combination treatment in HER2-enriched breast cancer and TNBC." (PMID 39768178, 2024). "Mechanistic studies showed that Cep70 enhances the ability of paclitaxel to induce apoptosis in breast cancer cells." (PMID 28632150, 2017). "Recent studies have shown that Cep70 regulates mitotic spindle organization and participates in the development and progression of breast cancer." (PMID 28632150, 2017). "We found that Cep70 expression level is related to paclitaxel sensitivity in breast cancer cell lines." (PMID 28632150, 2017). "Herein, we provide the first evidence that Cep70 modulates the sensitivity of breast cancer cells to paclitaxel." (PMID 28632150, 2017). "The expression level of Cep70 negatively correlated with the IC50 values of paclitaxel in breast cancer cells (r = −0.851, p = 0.031)." (PMID 28632150, 2017). "The present study investigated the potential mechanism of how Cep70 modulates paclitaxel sensitivity of breast cancer cells." (PMID 28632150, 2017). "We demonstrate that Cep70 enhances the ability of paclitaxel to induce apoptosis in breast cancer cells." (PMID 28632150, 2017). "We detected the protein level of Cep70 in six breast cancer cell lines (Hs578T, BT474, MDA-MB-231, T47D, MCF7, BT549) by immunoblotting, and found that the expression of Cep70 is different in these cell lines." (PMID 28632150, 2017). "Cell proliferation assays show that Cep70 expression correlates with paclitaxel sensitivity in breast cancer cell lines." (PMID 28632150, 2017). "It is shown that centrosomal protein 70 (Cep70) plays a critical role in the development and progression of breast cancer." (PMID 28632150, 2017). "Our previous worked show that centrosomal protein 70 (Cep70) regulates breast cancer growth and metastasis." (PMID 28632150, 2017). "To further verify the function of Cep70 in paclitaxel sensitivity, we reduced Cep70 expression level in breast cancer cells." (PMID 28632150, 2017). "Our findings demonstrate that Cep70 modulates the sensitivity of breast cancer cells to paclitaxel." (PMID 28632150, 2017). "It has been reported that Cep70 participates in the development and progression of breast cancer." (PMID 28632150, 2017). "It will be worthwhile to investigate whether the expression level of Cep70 in breast cancer tissues correlates with the pathological response of tumors to paclitaxel-based chemotherapy." (PMID 28632150, 2017). "Paclitaxel-treated cells are known to undergo apoptosis, we thus checked whether Cep70 affects the activity of paclitaxel to trigger apoptosis in breast cancer cells." (PMID 28632150, 2017). "Here we provide evidence that Cep70 is a mediator of paclitaxel sensitivity in breast cancer." (PMID 28632150, 2017). "Although paclitaxel sensitivity can vary between cancer lines for reasons not fully understood, these results suggest that Cep70 expression level may be a factor in the sensitivity to paclitaxel in breast cancer cells." (PMID 28632150, 2017). "Therefore, we hypothesized that the abnormal expression of Cep70 might influence the sensitivity of breast cancer cells to paclitaxel." (PMID 28632150, 2017). "Given our previous finding that Cep70 regulates microtubule stability, we speculate that Cep70 might modulate paclitaxel sensitivity in breast cancer cells by enhancing the ability of paclitaxel to stimulate microtubule assembly and stabilization, and then cause mitotic arrest and apoptosis." (PMID 28632150, 2017). "TGLI1 and STAT3 transcription factors interact to co-regulate target genes, Cep70, UPF3A, and RRas2, to mediate aggressive phenotypes in breast cancer." (PMID 39768178, 2024).
Azoospermia (2 papers, 2023 to 2025). Absence of any measurable level of sperm,whereby spermatozoa cannot be observed even after centrifugation of the semen pellet. "In that study, the authors found that CEP70 deficiency leads to male infertility in mice, which is associated with abnormalities in sperm flagellum, head and acrosome, and heterozygous mutations of CEP70 in four azoospermia patients were detected." (PMID 36967801, 2023).
male infertility (2 papers, 2023 to 2025). The inability of the male to effect fertilization of an ovum after a specified period of unprotected intercourse. "Future cases are needed to corroborate the proposed link of CEP70 mutations with male infertility in order to use it as a target for genetic counseling and diagnosis of male infertility." (PMID 36967801, 2023). "A recent study suggested that Cep70−/− in mice caused male infertility, which resulted in abnormal acrosome structure and abnormal flagella." (PMID 36967801, 2023). "In conclusion, the current study is the report of CEP70 mutation-related male infertility in humans with a recessive inheritance pattern, similar to the mouse model." (PMID 36967801, 2023). "Therefore, it is plausible that the variants of CEP70 are recessively inherited to produce pathogenicity in male infertility." (PMID 36967801, 2023). "Biallelic mutations of CEP70 might be a novel genetic cause of human male infertility, which could potentially serve as a basis for genetic counseling and diagnosis of male infertility." (PMID 36967801, 2023). "Our findings revealed an undiscovered recessive inheritance pattern of CEP70 mutations in human male infertility, which may provide new genetic evidence for the diagnosis and treatment of male infertility cases." (PMID 36967801, 2023). "Our findings suggest that CEP70 mutations might be related to male infertility in a recessive inheritance pattern." (PMID 36967801, 2023). "However, only one study has suggested that loss of CEP70 function is involved in male infertility." (PMID 36967801, 2023). "However, the role of CEP70 in human male infertility is limited." (PMID 36967801, 2023).
pancreatic cancer (2 papers, 2016 to 2022). "Collectively, these data demonstrate that ectopic expression of Cep70 causes microtubule disorganization and multipolar spindle formation in pancreatic cancer cells." (PMID 26893288, 2016). "Collectively, these data indicate that Cep70 promotes pancreatic cancer cell proliferation and inhibits apoptotic cell death." (PMID 26893288, 2016). "Consistent with the immunohistochemical results, Cep70 expression was up-regulated in all of these pancreatic cancer cell lines as compared to normal pancreas." (PMID 26893288, 2016). "Our data further show that ectopic expression of Cep70 in pancreatic cancer cells results in the mislocalization of centrosomal proteins, including γ-tubulin and pericentrin, and the formation of intracellular aggregates." (PMID 26893288, 2016). "Cep70 expression correlates with clinicopathological parameters of pancreatic cancer, including histological grade, pathological tumor node metastasis stage, lymph node metastasis, and carbohydrate antigen 19-9 level." (PMID 26893288, 2016). "To investigate the mechanism for elevated Cep70 expression in pancreatic cancer, we examined Cep70 mRNA level by quantitative real-time RT-PCR." (PMID 26893288, 2016). "Only 7.4% of normal pancreatic tissues showed high expression of Cep70, whereas 77.6% of pancreatic cancer tissues had high expression." (PMID 26893288, 2016). "At present, the precise molecular mechanisms of how Cep70 overexpression leads to centrosome abnormality in pancreatic cancer cells remain elusive." (PMID 26893288, 2016). "Since the centrosome plays a crucial role in bipolar spindle formation, we then studied the effect of Cep70 overexpression on the mitotic spindle in pancreatic cancer cells." (PMID 26893288, 2016). "Compared with normal pancreatic tissues, the level of Cep70 mRNA in pancreatic cancer tissues was remarkably increased, with an average of 12-fold increase." (PMID 26893288, 2016). "The present study demonstrates a critical role for Cep70 in pancreatic cancer cell proliferation and tumor growth in mice." (PMID 26893288, 2016). "In this scenario, it will be interesting to investigate in the future the effect of Cep70 overexpression on the molecular architecture and function of the centrosome, especially in the setting of pancreatic cancer pathogenesis." (PMID 26893288, 2016). "To substantiate the significance of Cep70 in pancreatic tumorigenesis, we altered the expression of Cep70 in pancreatic cancer cells and then injected these cells subcutaneously into the flank of athymic nude mice." (PMID 26893288, 2016). "To confirm the role of Cep70 in pancreatic cancer cell proliferation, we performed bromodeoxyuridine (BrdU) incorporation assay." (PMID 26893288, 2016). "By quantitative real-time PCR analysis, we found that Cep70 gene copy number in pancreatic cancer tissues was similar to that in normal pancreatic tissues." (PMID 26893288, 2016). "To further examine the involvement of Cep70 in pancreatic cancer, we investigated its expression in four human pancreatic cancer cell lines, including AsPC1, PANC1, CFPAC1, and BxPC3." (PMID 26893288, 2016). "Consistent with our quantitative real-time RT-PCR results, the Ishikawa dataset showed that the level of Cep70 mRNA was significantly increased in pancreatic cancer tissues, as compared to normal pancreas." (PMID 26893288, 2016). "Our study thus unravels a critical role for Cep70 in pancreatic cancer and suggests Cep70 as a potential biomarker and therapeutic target for this deadly disease." (PMID 26893288, 2016). "By sulforhodamine B staining assay, which reflects the index of cell proliferation, we found that depletion of Cep70 markedly inhibited the proliferation of pancreatic cancer cells." (PMID 26893288, 2016). "To dissect the role of Cep70 in pancreatic cancer, we first examined its expression in human pancreatic cancer tissues by immunohistochemical staining." (PMID 26893288, 2016).
pancreatic cancer (continued). "We found that Cep70 siRNAs dramatically reduced the ability of pancreatic cancer cells to form colonies in soft agar, which was remarkably restored by exogenous expression of Cep70." (PMID 26893288, 2016). "Our data also show that Cep70 overexpression in pancreatic cancer cells results in the mislocalization of γ-tubulin and pericentrin and formation of protein aggregates." (PMID 26893288, 2016). "We first performed colony formation assay in soft agar to assess whether Cep70 is required for anchorage-independent growth of pancreatic cancer cells." (PMID 26893288, 2016). "Since Cep70 localization at the centrosome depends on its interaction with γ-tubulin, we first examined the effect of Cep70 overexpression on γ-tubulin localization in pancreatic cancer cells." (PMID 26893288, 2016). "In this study, we demonstrate that Cep70 is highly expressed in pancreatic cancer tissues." (PMID 26893288, 2016). "Next, we investigated whether Cep70 expression correlates with the clinicopathological parameters of pancreatic cancer." (PMID 26893288, 2016). "In this study, we reveal that the expression of Cep70 is elevated in pancreatic cancer tissues." (PMID 26893288, 2016). "We next studied the effect of Cep70 on pancreatic cancer cell proliferation." (PMID 26893288, 2016). "Interestingly, Cep70 expression correlates with clininopathological parameters of pancreatic cancer." (PMID 26893288, 2016). "The next question then is whether Cep70 plays a role in the development of pancreatic cancer." (PMID 26893288, 2016). "To understand the molecular mechanism by which ectopic expression of Cep70 promotes pancreatic tumorigenesis, we transfected GFP-Cep70 into pancreatic cancer cells and examined the localization of centrosomal proteins." (PMID 26893288, 2016). "Together, these results suggest that the aberrant expression of Cep70 in pancreatic cancer is independent of its gene copy number gain." (PMID 26893288, 2016). "In addition, there was a correlation between the expression of Cep70 and the level of carbohydrate antigen 19-9 (CA19-9), the standard serum marker of pancreatic cancer." (PMID 26893288, 2016). "The expression of Cep70 in pancreatic cancer tissues was significantly up-regulated as compared with normal pancreatic tissues." (PMID 26893288, 2016). "Despite the significant up-regulation of Cep70 mRNA expression, its gene copy number is not obviously changed in pancreatic cancer tissues, suggesting that Cep70 up-regulation in this disease is not due to gene amplification." (PMID 26893288, 2016).
B cell deficiency (1 paper, 2016). A broad classification of disorders where circulating numbers of B lymphocytes are decreased or ineffective. "Interestingly, while in the model of B cell deficiency, the DC genes are highly enriched with causal regulatory genes, there was only one key driver in cervical cancer (CEP70), despite the DC genes in this system still seeming to play a regulatory role overall." (PMID 28163897, 2016).
Bardet-Biedl syndrome (1 paper, 2009). A ciliopathy with multisystem involvement. "The resemblance of both cep70 and cep131 morphants to those of zebrafish IFT57 and IFT88 makes the two proteins candidates for genes mutated in inherited human diseases similar to Bardet-Biedl syndrome in which cilia in a number of tissues are affected." (PMID 19254375, 2009).
infertile (1 paper, 2023). "In this study, we identified biallelic mutations of CEP70 in two unrelated infertile male individuals with oligoasthenoteratozoospermia that followed a recessive inheritance pattern." (PMID 36967801, 2023). "The infertile patient with CEP70 mutations showed amorphous heads, abolished acrosomes, and anomalous flagella morphology in sperm." (PMID 36967801, 2023). "Intriguingly, in this study, biallelic mutations of CEP70 in two infertile men followed a recessive inheritance pattern." (PMID 36967801, 2023).
oligoasthenoteratozoospermia (1 paper, 2023). A form of male infertility that is characterized by a combination of low number or oligozoospermia, poor motility or asthenozoospermia, and abnormal shape or teratozoospermia of sperms. "In the present study, we identified two novel biallelic variants in CEP70 that are responsible for human oligoasthenoteratozoospermia." (PMID 36967801, 2023).
Type 2 diabetes (1 paper, 2024). "Other interesting CEP70 interactors are involved for example in insulin receptor binding, which could also serve as a link to the ALMS phenotypic occurrence of Type 2 diabetes." (PMID 38122899, 2024).
tumor (54 papers, 2010 to 2025). "We found that the tumor volume in Cep70 siRNA groups was much smaller than that in the control siRNA group." (PMID 26893288, 2016). "Cep70 siRNAs dramatically reduced tumor weight, which was abolished by exogenous expression of Cep70." (PMID 26893288, 2016). "We found that the level of Cep70 significantly correlated with histological grade, pathological tumor node metastasis (pTNM) stage, and lymph node (LN) metastasis." (PMID 26893288, 2016). "Cep70 also stimulates colony formation in soft agar and enhances tumor growth in mice." (PMID 26893288, 2016). "Notably, exogenous expression of Cep70 resulted in a substantial increase in tumor volume." (PMID 26893288, 2016).
cancer (14 papers, 2014 to 2025). A tumor composed of atypical neoplastic, often pleomorphic cells that invade other tissues. "Similarly, upregulated CEP70 expression, as induced by antibiotic treatment in this study, has been implicated in the pathophysiology of numerous cancers." (PMID 35630307, 2022). "It has also been suggested that the role Cep70 plays in cancer might be a consequence of the interaction of Cep70 with other microtubule associated proteins." (PMID 28632150, 2017). "However, the role Cep70 plays in paclitaxel sensitivity of cancer cells remains unknown." (PMID 28632150, 2017).
CEP70 also shares sentences with these, for which no sentence is quoted: acute lymphoblastic leukemia (2 papers); acute myeloid leukemia (2); lymphoma (2); melanoma (2); asthenozoospermia (1); Burkitt lymphoma (1); cervical cancer (1); colon cancer (1); hematologic malignancies (1); hepatocellular carcinoma (1); leukemia (1); lung adenocarcinoma (1); multiple myeloma (1); neuroblastoma (1); non-Hodgkin lymphoma (1); ovarian carcinoma (1); viral infection (1).